MLKL (mixed lineage kinase domain like pseudokinase)
Diseases named in the same sentence as MLKL in open-access papers (continued):
Sharing a sentence is not in itself a finding about the gene and the disease.
ischemic stroke (13 papers, 2019 to 2024). A stroke disorder caused by obstruction of blood flow to the brain, due to thrombotic (local blood clot formation) or embolic (due to a blood clot or other material traveling from another site) event. "Importantly, the simultaneous knockdown of Ripk1 and Nsf exerted neuroprotective effects on ischemic stroke by modulating the RIPK1/RIPK3/MLKL signaling pathway associated with necroptosis in neurons." (PMID 38919602, 2024). "Enhanced HIF-1α levels after ischemic stroke appear to be involved in RIPK3/MLKL activation, leading to activation of the NLRP3 inflammasome." (PMID 38674050, 2024). "The simultaneous knockdown of Ripk1 and Nsf exerts its effects on ischemic stroke through the RIPK1/RIPK3/ mixed lineage kinase domain-like protein (MLKL) signaling pathway involved in necroptosis." (PMID 38919602, 2024). "Several studies have demonstrated that RIPK1, RIPK3 and MLKL participate in the pathogenesis of ischemic stroke after the activation of DRs." (PMID 38026442, 2023). "In previous studies, necroptosis was found to contribute to ischemic stroke by intervening in the RIPK1/RIPK3/MLKL signaling pathway in neurons and microglia." (PMID 38026442, 2023). "By intervening in the RIPK1/RIPK3/MLKL pathway, previous studies have demonstrated that necroptosis contributes to ischemic stroke." (PMID 38026442, 2023). "Further in vivo mechanistic studies are required to validate the therapeutic potential of MLKL in secondary neurodegeneration after ischemic stroke." (PMID 37904209, 2023). "In this study, we explored the effects of MLKL inhibitor NSA on ischemic stroke as well as its potential mechanisms." (PMID 37964865, 2023). "Recently, it was shown for the first time that p-RIPK1- (Ser166) and RIPK3/MLKL-dependent necroptosis pathways are activated in the modeling of ischemic stroke." (PMID 35054920, 2022). "Nec-1 treatment was able to protect against ischemic neuronal death by inhibiting RIPK1-mediated RIPK3/MLKL-dependent necroptosis in rat brains following ischemic stroke." (PMID 31440386, 2019). "HIF-1α also regulates necroptosis-related proteins, such as RIPK3 and MLKL, in ischemic stroke." (PMID 38674050, 2024). "In the middle cerebral artery occlusion (MCAO) model in vivo and the oxygen–glucose deprivation/re-oxygenation (OGD/R) cellular model in vitro, blocking the RIPK1/RIPK3/MLKL pathway could effectively alleviate ischemic stroke injuries." (PMID 38026442, 2023). "RIP1K downstream proteins RIP3K and MLKL may also play an important role in the ischemic stroke formation of glial scars." (PMID 33629276, 2021). "In addition, the present study also revealed that RIP1K downstream proteins RIP3K and MLKL may play an important role in the ischemic stroke formation of glial scars." (PMID 33629276, 2021). "Recently, we firstly reported that ischemic stroke leads to astrocytic necrotic cell death, showing increased expression of RIP1K, RIP3K, and MLKL." (PMID 37964865, 2023). "The results showed that ischemic stroke induced the increase of RIPK3, MLKL and p-MLKL (Ser 345) expression levels in the ipsilateral striatum at 24 h after MCAO." (PMID 31440386, 2019). "Knockout of receptor-interacting serine/threonine protein kinase 3 (RIPK3) or mixed-lineage kinase domain-like protein (MLKL), the key regulators of the necroptotic pathway, can reduce the severity of renal ischemia‒reperfusion (I/R) injury and ischemic stroke." (PMID 36828808, 2023). "Necroptosis revealed that the programmed cell death necrosis mechanism is induced in ischemic stroke, triggered by the phosphorylation of receptor-interacting protein kinase-1 (RIPK1), receptor-interacting protein kinase 3 (RIPK3), and mixed lineage kinase domain-like (MLKL)." (PMID 37681864, 2023).
ischemic stroke (continued). "How the nuclear complex of MLKL and RIP3K plays a role and whether the nuclear envelope co-localization of MLKL and RIP3K exerts independently at nuclear envelope in necroptosis after ischemic stroke remain to be investigated in the very near future." (PMID 37964865, 2023). "RIPK3−/− did not reduce neuronal death in an ischemic stroke model, but RIPK3−/− mice had reduced biochemical markers of apoptosis in a CCI model, whereas MLKL−/− mice had markedly reduced acute neuronal death after ICH." (PMID 34753914, 2021).
Stroke (13 papers, 2017 to 2025). Sudden impairment of blood flow to a part of the brain due to occlusion or rupture of an artery to the brain. "Clearly, serum MLKL levels were substantially elevated during fifteen days, as compared to controls; moreover, its highest levels occurred at Day 3 after stroke." (PMID 40079614, 2025). "Studies identified MLKL is a promoting factor in this process, suggesting its potential as a therapeutic target to mitigate posthemorrhagic stroke damage." (PMID 39902279, 2024). "Degradation of MLKL after stroke has also been shown to have neuro-protective effects in preclinical models of cerebral ischemia." (PMID 33142926, 2020). "Zhou and colleagues found, using the murine MCAO model of stroke, that MLKL protein is significantly increased in infarcted tissue 12 to 48 h post ischemia/reperfusion." (PMID 33142926, 2020). "Further investigation is needed to confirm the decreased interaction between RIP3 and MLKL following experimental stroke." (PMID 30988281, 2019). "Moreover, the found that peri-procedure administration of necrosulfonamide (NSA) significantly decreases infarct volume and MLKL protein level, while significantly improving post-stroke neurologic scores." (PMID 33142926, 2020). "Our results also showed that TRAF2 formed more complex with MLKL following experimental stroke, suggesting that TRAF2 may inhibit necroptosis by abating the association between MLKL and RIP3." (PMID 30988281, 2019). "This region also displays a marked increase in phospho-MLKL staining indicating the presence of necroptosis and suggesting that cell death sequelae following occlusion are of different modalities, as would be expected with an acute inflammatory response after stroke." (PMID 38653992, 2024). "Thus, MLKL may be a potential therapeutic target for stroke." (PMID 28978125, 2017). "Finally, overexpression of Tmem30a also reduced apoptosis marker cleaved caspase‐3 (CC3) and necroptosis marker (p‐MLKL) and increased anti‐apoptosis marker Bcl‐xL and BCL‐2 in the penumbra regions 24 h after stroke." (PMID 40104262, 2025). "Although there have not been other reports about the relationship between serum MLKL levels and the severity of ICH, this study can offer pilot evidence to deduce that serum MLKL may be recommended as a predictor for mirroring stroke severity following ICH." (PMID 40079614, 2025).
liver disease (12 papers, 2016 to 2026). "MLKL has been implicated in liver disease pathogenesis by regulating hepatocyte necroptosis." (PMID 36765043, 2023). "Several previous studies have shown that inhibition of RIPK1 or MLKL can retard the progression of liver disease." (PMID 37828052, 2023). "A necroptosis-independent role of MLKL in the regulation of liver diseases has been revealed in recent studies." (PMID 36765043, 2023). "Although the role of RIP3 has been studied in multiple models of liver injury, much less is known about the role of MLKL, the downstream effector of necroptotic cell death, in liver disease." (PMID 33616081, 2021). "We next examined VAT and liver pathology to discern how MLKL drives obesity and liver disease." (PMID 39532538, 2025). "The findings demonstrate that RIP3, RIP3 kinase activity, and MLKL play crucial roles in modulating hepatic ER stress responses and cell death pathways, with potential implications for the pathogenesis and treatment of ALD and other ER stress-related liver diseases." (PMID 41040277, 2025).
psoriasis (12 papers, 2020 to 2025). An autoimmune condition characterized by red, well-delineated plaques with silvery scales that are usually on the extensor surfaces and scalp. "NET formation and associated activation of RIPK3/MLKL has been observed in neutrophil-rich tissue samples from patients with cutaneous vasculitis and psoriasis." (PMID 35929827, 2022). "Taken together, these results indicate that saracatinib alleviated IMQ-induced psoriasis by inhibiting the phosphorylation of MLKL." (PMID 38331847, 2024). "Taken together, these findings indicate that saracatinib inhibits necroptosis by targeting MLKL, providing a potential therapeutic approach for skin inflammation-related diseases such as psoriasis." (PMID 38331847, 2024). "In an imiquimod (IMQ)-induced psoriasis mouse model, saracatinib effectively blocked MLKL phosphorylation and inflammatory responses in vivo." (PMID 38331847, 2024). "In an IMQ-induced psoriasis mouse model, saracatinib effectively blocked MLKL phosphorylation and inflammatory responses in mice." (PMID 38331847, 2024). "Immunofluorescence of TUNEL and immunohistochemical labeling of active caspase-3, RIPK1, and MLKL suggest that necroptosis mainly occurs in the upper epidermis, which is similar to the results in psoriasis patients." (PMID 32075957, 2020). "Necroptosis, a form of regulated necrosis mediated by receptor-interacting protein kinase 1 (RIPK1), RIPK3, and mixed-lineage kinase domain-like pseudokinase (MLKL), plays a central role in the inflammatory cascade of psoriasis and is also implicated in other inflammatory diseases." (PMID 40906403, 2025). "Moreover, saracatinib decreased IMQ-induced MLKL phosphorylation in mouse skin tissues, which implied that saracatinib ameliorated IMQ-induced psoriasis by inhibiting MLKL." (PMID 38331847, 2024). "Importantly, the hallmarks of necroptosis, such as phosphorylation of RIPK3 and MLKL were significantly increased in the epidermis of human psoriasis lesions." (PMID 38331847, 2024). "The mixed lineage kinase domain-like protein (MLKL) is the downstream mediator of the necroptosis process and also the molecular target for saracatinib that has shown promising results in the treatment of psoriasis, an autoimmune disease." (PMID 38674150, 2024). "Thus, our work reveals that saracatinib inhibited necroptosis and ameliorated IMQ-induced psoriasis in mice by targeting MLKL." (PMID 38331847, 2024). "A recent study has demonstrated necroptosis’s crucial role in psoriasis pathogenesis, evidenced by the significant upregulation of RIPK1 and MLKL throughout all epidermal layers in human psoriatic lesions." (PMID 40332377, 2025). "In pneumonia and psoriasis, S. aureus infection induces necroptosis through RIP1/RIP3/MLKL signaling." (PMID 35878202, 2022). "In psoriasis, S. aureus infection can also be mediated by the RIPK1/RIPK3/MLKL-mediated necrotizing apoptosis of keratinocytes, and RIPK1 mediates keratinocyte death via TNF." (PMID 35878202, 2022).
cervical squamous cell carcinoma (11 papers, 2018 to 2024). A squamous cell carcinoma arising from the cervical epithelium. "MLKL is a prognostic biomarker for cervical squamous cell carcinoma and has recently been identified as a key RIPK3 downstream component of TNF-induced necroptosis." (PMID 36685937, 2022). "MLKL was initially identified as a key mediator of TNF-induced necroptosis and can be used to assess the prognosis of patients with cervical squamous cell carcinoma, and TNF is also important for immune and cellular homeostasis in mammals." (PMID 36685937, 2022).
ischemia (11 papers, 2017 to 2025). A hypoperfusion of the BLOOD through an organ or tissue caused by a PATHOLOGIC CONSTRICTION or obstruction of its BLOOD VESSELS, or an absence of BLOOD CIRCULATION. "In conclusion, our study was the first to demonstrate that p-RIPK1 (Ser166) increases in the brain after ischemia, which then activated the RIPK3/MLKL-dependent necroptotic signaling pathway to cause neuronal death." (PMID 31440386, 2019). "In this study, we showed that p-RIPK1 (Ser166) induced by ischemia triggered the RIPK3/MLKL-dependent necroptotic pathway." (PMID 31440386, 2019). "The levels of three core components of necrotic pathways, RIPK1, RIPK3 and MLKL significantly increased during 6–24 h of ischemia developed after the beginning of reperfusion, while cleaved caspase-8 was reduced." (PMID 30158627, 2018). "To explore its role in neurological diseases, we measured MLKL protein expression after ischemia injury in a mouse model." (PMID 28978125, 2017). "Consistent with staining results, Western blot analysis showed that NSA treatment markedly reduced MLKL expression during ischemia injury (P<0.05)." (PMID 28978125, 2017). "Additionally, BCP treatment inhibited the phosphorylation of MLKL at 48 h of reperfusion following focal ischemia in vivo." (PMID 29123466, 2017). "We also demonstrated that ischemia-induced RIPK1-mediated RIPK3/MLKL necroptosis was specific because Nec-1 treatment could significantly inhibit ischemia-induced increase of RIPK3, MLKL and p-MLKL expressions as well as attenuate ischemic brain injury via inhibition of RIPK1 kinase activity." (PMID 31440386, 2019). "Inhibition of MLKL by intraperitoneal administration of NSA significantly reduced infarct volume and improved neurological deficits after 75 min of ischemia and 24 h of reperfusion." (PMID 28978125, 2017). "We next tested whether RIP3K and MLKL, RIP1K downstream proteins, are involved in ischemia-induced reactive astrogliosis." (PMID 33629276, 2021).
asthma (10 papers, 2020 to 2025). "IFN-β deficiency at asthma exacerbation promotes mixed lineage kinase domain-like protein (MLKL)-mediated necroptosis." (PMID 36225449, 2022). "To further investigate the role of necroptosis signaling in asthma progression and its impact on downstream mechanisms, we performed mRNA profile analysis on WT and MLKL knockout OVA-induced mice, screening 505 down-regulated and 48 up-regulated genes." (PMID 38987753, 2024). "The pathological changes in asthma induced by recombinant TL1A were partially reversed by MLKL knockout." (PMID 38987753, 2024). "We have demonstrated the upregulation and activation of necroptosis-dependent proteins, RIPK3 and MLKL, in the airway epithelia of asthma patients and animal models." (PMID 38987753, 2024). "The results showed that asthma sensitivity was reduced in IRF7−/− mice by the drug inhibition of RIPK1- or MLKL-induced tracheal smooth muscle remodeling, mucus hypersecretion, and reduced eosinophilic inflammation." (PMID 35967568, 2022). "Using house dust mite (HDM) extract allergens and a stimulation-induced asthma mouse model, the development of asthma pathology was prevented in mice by the inactivation of RIPK1 kinase expression and RIPK3 or MLKL deficiency." (PMID 35967568, 2022). "Inhibition of the RIPK1 and MLKL can ameliorate the severity of viral bronchiolitis in mice and prevent the later progression to asthma." (PMID 34977874, 2021). "Inhibition of necroptosis by GSK872 or MLKL knockout ameliorated OVA-induced asthma changes." (PMID 38987753, 2024). "Inhibition of the RIPK1 and MLKL could protect the mice from asthma." (PMID 34977874, 2021). "Single-cell transcriptomics of severe asthma biopsies has revealed epithelial cells co-expressing GSDMD and MLKL, correlating with neutrophilia and impaired steroid signaling, indicating PANoptosis as a key contributor to refractory phenotypes." (PMID 41394843, 2025). "We compared p-MLKL and p-RIPK3 protein levels in human lung tissue sections obtained from 4 healthy controls and 4 asthma patients." (PMID 38987753, 2024). "In severe, refractory asthma, this interplay may necessitate complex co-targeting strategies (e.g., simultaneously inhibiting GSDMD and the necroptosis mediator MLKL), adding layers of complexity to therapeutic development." (PMID 41394843, 2025). "Next, using MLKL knockout mice and the RIPK3 inhibitor GSK872, we investigated the effects of TL1A on airway inflammation and airway barrier function through the activation of necroptosis in experimental asthma." (PMID 38987753, 2024). "Furthermore, blocking necroptosis with GSK872 and knocking out MLKL both preceded OVA-challenge, indicating that blocking necroptosis may prevent airway damage in asthma." (PMID 38987753, 2024). "Here, we found that deficiency of PTRF could reduce lung IL-33, ZBP1, phosphor-receptor-interacting protein kinase 3 (p-RIPK3), and phosphor-mixed lineage kinase domain-like (p-MLKL) (necroptosis executioner), and airway inflammation in an HDM-induced asthma mouse model." (PMID 37454215, 2023). "Lack of RIPK1 kinase activity or RIPK3 or MLKL deficiency did not protect mice with intact FADD signaling from HDM-induced airway inflammation, showing that RIPK1-RIPK3-MLKL-mediated necroptosis does not play an important role in HDM-induced asthma in wild type mice." (PMID 34045680, 2021). "Serum concentrations of p-MLKL and RIPK3 were significantly elevated in asthma patients compared to healthy controls, but no significant change in the level of HMGB1 was observed (data not shown)." (PMID 38987753, 2024). "One of the limitations of this study is that it is difficult to obtain BALF samples from patients with asthma, and serum levels of RIPK3 and p-MLKL may not be fully representative or conclusive." (PMID 38987753, 2024).
asthma (continued). "In a mouse model of asthma exacerbations induced by in house dust mite for inflammation and double‐stranded RNA for exacerbation, RIPK3 and phosphorylation of MLKL were increased in IFN‐β‐/‐ mice, so the absence of IFN‐β may augment markers of necroptotic cell death at exacerbation." (PMID 34977874, 2021).
myocardial infarction (10 papers, 2017 to 2026). Gross necrosis of the myocardium, as a result of interruption of the blood supply to the area, as in coronary thrombosis. "Necroptosis-associated proteins, such as RIPKs andphosphorylated MLKL, were significantly upregulated in end-stage heart failurecaused by DCM and heart failure resulting from myocardial infarction (MI).Phosphorylated MLKL was higher in DCM than in CAD." (PMID 40776946, 2025). "Therefore, here we analyzed the expression of RIP1, pSer227-RIP3, RIP3 and cytotoxic phosphorylated forms of MLKL (pThr357-MLKL and pSer358-MLKL) in human myocardium from end-stage HF patients due to cardiomyopathy post myocardial infarction (CAD) and dilated cardiomyopathy (DCM)." (PMID 28454582, 2017). "Arctiin significantly reduced myocardial I/R injury (myocardial infarction and creatine kinase release), while decreasing the levels of necroptosis-related proteins (RIPK1/p-RIPK1, RIPK3/p-RIPK3, and MLKL/p-MLKL) in the hearts of I/R-treated rats." (PMID 37504559, 2023).